BCL2 (BCL2 apoptosis regulator)
Diseases named in the same sentence as BCL2 in open-access papers (continued):
Sharing a sentence is not in itself a finding about the gene and the disease.
neuroblastoma (continued). "Although we did observe apoptosis in high BCL2-expressing neuroblastoma cells, similar to GBM cells, BAU-243 did not induce apoptosis of neuroblastoma cells as well." (PMID 36309485, 2022). "Subsequently, BCL-2 silencing in neuroblastoma cells was shown to induce apoptotic cell death while ABT-199 also synergised with fenretinide in both neuroblastoma cell lines and PDX models expressing high BCL-2 levels, where improved event-free survival was demonstrated." (PMID 35568716, 2022). "Therefore, when we assess BCL2 expression levels among several cell lines, we observed that GBM cells have low BCL2 expression, while neuroblastoma cells express BCL2 abundantly." (PMID 36309485, 2022). "Therefore, we assessed the BCL2 expression of several cell lines including GBM cell lines A172, YKG1, LN18, U87MG, neuroblastoma cell line SHSY-5Y, promyelocytic cell line HL-60, and endothelial cell line HUVEC." (PMID 36309485, 2022). "The over-expression of UTP18 in neuroblastoma promotes the expression of VEGF, Bcl-2, HIF1α, and c-MYC, improves the adaptability of tumor cells to environmental stress, and reduces the death of neuroblastoma cells after exposure to hydrogen peroxide, hypoxia or glucose deprivation." (PMID 35265610, 2022). "No change in the expression of Bcl-2 was observed in neuroblastoma and squamous cell carcinoma after BA treatment." (PMID 34770786, 2021). "A similar modulatory effect by OA on BCL-2 and BAX has been observed in neuroblastoma cells." (PMID 33071785, 2020). "Here, we investigated the role of BCL-2, BCL-XL and MCL-1 in neuroblastoma." (PMID 32203216, 2020). "Previous studies have mainly been performed with the BCL-2/BCL-XL inhibitors ABT-737 and ABT-263, and the sensitivity of neuroblastoma cells to these BH3-mimetics has largely been attributed to an inhibition of BCL-2 rather than BCL-XL." (PMID 32203216, 2020). "Further studies analyzed BCL2–PrPc interaction by Co-IP from transiently transfected neuroblastoma cells with cytosolic PrPc and revealed that BCL2 was not co-precipitated with wildtype PrPc." (PMID 32992764, 2020). "Similarly, in neuroblastoma cells, HIF-1α-dependent induction of miR-210 triggered by oxygen/glucose deprivation has been demonstrated to target the 3’UTR of B-cell CLL/lymphoma 2 (Bcl-2) and sequentially promote hypoxia-induced neural apoptosis." (PMID 32014012, 2020). "In contrast to choroid plexus tumors, PNETs, neuroblastomas, astrocytomas, and oligodendrogliomas gliomatosis cerebri were almost negative for both Bcl-2 and Bcl-xL." (PMID 32260403, 2020). "In neuroblastoma models, I-BET 762 triggered apoptosis via BET inhibition of both MYCN and Bcl-2." (PMID 30906568, 2019). "ABT-737, that binds with subnanomolar affinity to Bcl-2, Bcl-W and Bcl-xL, but has no appreciable affinity for Mcl-1, has shown to induce cell death in neuroblastomas." (PMID 30885150, 2019). "This assumption is confirmed by a recent study, which demonstrated that neuroblastoma cells might survive ABT-199 treatment, a specific Bcl-2 inhibitor, due to acute upregulation of Mcl-1." (PMID 30885150, 2019). "In human neuroblastoma cells, N-MYC and Bcl-2 co-expression induced MMP-2 secretion and activation." (PMID 30135355, 2018). "In contrast to the efficacy of monotherapy, we found that the venetoclax/idasanutlin combination is synergistic independent of MCL1 or BCL2 expression levels, suggesting a wide applicability in neuroblastoma." (PMID 28915653, 2017). "Therefore, we determined BCL2 and MCL1 RNA and protein expression levels by RT-qPCR and Western Blotting, respectively, in a panel of neuroblastoma cell lines." (PMID 28915653, 2017). "Since we evaluated protein levels in neuroblastoma cell lines with high BCL2 expression levels and not in MCL1-dependent cell lines, it cannot be excluded that MCL1 is downregulated by idasanutlin treatment in the latter." (PMID 28915653, 2017).
neuroblastoma (continued). "In order to assess whether combined treatment of ABT-263 and idasanutlin could have a broad therapeutic applicability in neuroblastoma, we evaluated both compounds in 10 human neuroblastoma cell lines with varying MCL1 and BCL2 expression levels." (PMID 28915653, 2017). "Analysis of two additional neuroblastoma cell lines revealed reduced Bcl-2 protein levels upon treatment with I-BET726, confirming the critical role of BET proteins in maintaining BCL2 expression." (PMID 24009722, 2013). "Previously, it has been reported that Bcl-2 promotes invasion and lung metastasis by inducing MMP-2 in NSCLC cells and coexpression of Bcl-2 and N-Myc induces MMP-2 secretion and activity in human neuroblastoma cells." (PMID 22748147, 2012). "Similar studies performed with human 293 kidney or SH-Sy5y neuroblastoma cells demonstrated significant reductions in bcl-2 (42% and 36.7%, resp.; P < .01), but no significant changes in the levels of FasR, FasL, or TNF-R1 expression (data not shown)." (PMID 20111737, 2009). "Mcl-1 was upregulated after bortezomib exposure in all neuroblastoma cell lines whereas no change was identified in Bcl2, XIAP, survivin and Bcl-xl expression after bortezomib treatment." (PMID 18534018, 2008). "In mouse neuroblastoma-derived NS20Y cells, DEHP exposure reduced the mRNA and protein expression of PI3K and AKT, concomitantly increasing the mRNA and protein expression of Cyt-c, Bax, Bak, and Caspase-3, while decreasing the mRNA and protein expression of Bcl-2." (PMID 41373866, 2025). "We found that in both SCLC and neuroblastoma, cell lines with higher NE scores were more resistant to drugs that target MEK, mTOR, XIAP, LCK, HSP90, and Abl but were more sensitive to BCL inhibitors, which inhibit anti-apoptotic B-cell lymphoma-2 (Bcl-2) family of proteins." (PMID 37255415, 2023). "Besides the inhibition of BCL2 with ABT199, also the inhibition of BCL-XL or MCL1 with their selective antagonists A1331852 or S63845 is able to induce apoptosis in multiple neuroblastoma cells including primary cells." (PMID 37723317, 2023). "Overexpression of Bcl-2 and Bcl-xL resulted in the reduction of TRAIL-induced cleavage of caspase-8 and Bid, cleaved blockage of caspase-3, -7, and -9 in non-small-cell lung cancer (NSCLC) and the cleavage of caspase substrates like PARP in glioblastoma, neuroblastoma, and breast cancer cell lines." (PMID 37065863, 2023). "However, BAU-243 did not trigger intrinsic apoptosis in high BCL2-expressing neuroblastoma cells as well." (PMID 36309485, 2022). "Moreover, growth and therapeutic resistance in neuroblastoma was shown to be mediated through the miR-15a/16-1–ERK and Bcl-2/Cyclin D1 pathways which supports our findings that miR-15a-5p may play a pivotal role in ECD development." (PMID 34785791, 2022). "Moreover, BCL-2 is known to be overexpressed in non-hematologic tumors as ovarian, neuroblastoma, colorectal, and HNSCC." (PMID 36142875, 2022). "We could show that the protein encoded by DLG2-isoform 7 could bind to LIN7A, and increased DLG2-isoform 7 gene expression increased the expression of LIN7A, this reduced neuroblastoma cell proliferation and viability, with increased BAX/BCL2 ratio indicating increased apoptosis." (PMID 33726762, 2021). "Finally, in none of the neuroblastoma cell lines was the expression of Bcl-2 modified significantly as a consequence of the treatment with melphalan." (PMID 34832966, 2021). "A previous study revealed that paclitaxel can induce apoptosis of human neuroblastoma cell line (NB-1 cells), which may be mediated by downregulation of Bcl-2 and upregulation of Bax." (PMID 34180747, 2021). "However, both treatments produced only slight changes in the levels of total BCL2 and BECLIN1 proteins, indicating that they cannot be used confidently as markers for immediate autophagy evaluation in neuroblastoma cells when only a single temporal point is available for testing." (PMID 32962733, 2020).
neuroblastoma (continued). "Additionally, neuroblastoma cells can acquire resistance to the BCL-2 inhibitor ABT-737 by upregulating EGFR and develop a dependence on MCL-1, which can be effectively countered by combining erlotinib with a BCL-2 inhibitor." (PMID 31150457, 2019). "Furthermore, treatments with isoproterenol decreased the expression of Bax and increased expression of Bcl2, suggesting that TRPM7 expression and function are modulated via isoproterenol, which is essential for the neurotoxin-induced survival of neuroblastoma cells." (PMID 32390858, 2020). "However, PKM2 also phosphorylates non-metabolic substrates, for example stabilizing Bcl-2 and influencing transcription via phosphorylation of histone 3, already demonstrated in neuroblastoma, and perturbation of these pathways may contribute to GSK3203591-mediated growth inhibition." (PMID 39313128, 2024). "We found that ATF5 knockdown reduced the expression of BCL-2 and MCL-1, but not of BMF, in adherent neuroblastoma cells." (PMID 38014922, 2023). "Consistently, in another study, ABT-737 showed single-agent activity against only BIM:BCL-2 and not BIM:MCL-1-primed neuroblastoma-derived xenografts." (PMID 31652776, 2019). "Independent of the neuroblastoma cell line tested, BAP1 expression promoted the downregulation of Bcl-2." (PMID 29686263, 2018). "We however observed increased protein levels of the apoptotic mediators PUMA and BAX upon idasanutlin treatment of neuroblastoma cells, but no downregulation of MCL1 protein or any effects on BCL2 protein abundance." (PMID 28915653, 2017). "Moreover, besides the candidate drug obatoclax mesylate, other BCL-2 inhibitors, which were not included in the GDSD dataset, such as venetoclax and navitoclax showed promising results in neuroblastoma-derived cell lines and tumors." (PMID 36634214, 2023). "To test the relative importance of Bcl2, Bcl-xL, and Mcl1, we used a small molecule chemical screen coupled with readouts for apoptotic cell death in two cell lines, the dopaminergic MN9D and the more commonly used non-dopaminergic neuroblastoma N2A cell line." (PMID 30479840, 2018). "After 24 h treatment of neuroblastoma cell lines CHP126, KCNR and SJNB12 with nanomolar concentrations ABT199, shifting of BIM from BCL-2 to the anti-apoptotic protein MCL-1 was observed while no sequestration of released BIM by the anti-apoptotic protein BCL-XL was observed." (PMID 27056887, 2016).
cervical carcinoma (217 papers, 1998 to 2026). A carcinoma arising from either the exocervical squamous epithelium or the endocervical glandular epithelium. "Literature on BCL2 is conflicting: some studies report decreased expression in advanced or high-risk lesions, while others show upregulation in early-stage cervical cancer." (PMID 41562704, 2026). "High BCL-2 expression is associated with resistance to apoptosis in various cancers, including cervical cancer." (PMID 39937205, 2025). "Among these E. faecium strains, KU22001 grown at 25°C was associated with the highest bax/bcl-2 ratio, effective apoptosis rate, cell cycle arrest in the G0/G1 phase, and condensation of the nucleus in the cervical cancer HeLa cell line." (PMID 38494869, 2024). "Its overexpression in cervical cancer tissues is associated with an increase in B-cell lymphoma 2 (Bcl-2 or BCL2) expression levels, by acting as a ceRNA of miR-744." (PMID 36290414, 2022). "There are publications indicating that in cervical cancer, the immunohistochemical expression of BCL2 and BAX is associated with the progression of the disease and the radiosensitivity of tumor cells." (PMID 34830452, 2021). "Bcl-2 up-regulation has been implicated in the resistance to cisplatin in a variety of cancer cell lines, however its role in cervical cancer is confounding." (PMID 26474854, 2015). "5ALA-PDT also caused a significant decrease in mRNA expression of Bcl-2 and increased the levels of Bax and Bad mRNA in cervical cancer in BALB/c nude mice." (PMID 23914299, 2011). "Thus, when assessing the prognosis of patients with primary cervical cancer and recurrent carcinoma, a positive staining for BCL2 was associated with a better 5-year survival rate." (PMID 34830452, 2021). "Prior studies have suggested that the increased caspase-3 activity in LUAD cells A549 and Calu3 is associated with the upregulation of miR-140-3p, while the decreased Bcl-2 is associated with the elevation of Bax and cleaved caspase-3 in cervical cancer cell Caski." (PMID 34818974, 2021). "Bcl-2 expression has been implicated in the resistance of various cancers to chemotherapy treatment, but evidence of its role in cervical cancer remains unclear." (PMID 26474854, 2015). "It increased Bax/Bcl-2 ratio and mitochondrial outer membrane permeability, caused the release of Cyt c into the cytoplasm, and activated Apaf-1 and caspase 3/9, which induced apoptosis in HeLa cells, and it is considered as a potential agent for the treatment of cervical cancer." (PMID 34680171, 2021). "The Bcl-2 protein family regulates apoptosis, with altered BCL2 expression playing a role in cervical cancer progression." (PMID 41562704, 2026). "The progression of premalignant cervical lesions to invasive malignancy is linked to the expression of BCL-2, and the prognostic value of BCL-2 as a predictor of treatment outcomes in cervical cancer have been evaluated via various studies." (PMID 41521222, 2026). "Another calcitriol-induced microRNA, miR-211, has been shown to trigger autophagy and autophagy-dependent apoptosis through the regulation of Bcl-2 in cervical cancer cells." (PMID 40168262, 2025). "The strong staining of Bcl‐2, VEGFα, and Ki‐67 was present in 92.6%, 91.6%, and 94.6%, respectively, in the cervical cancer sample." (PMID 41263059, 2025). "RCE-4, a spirostanol saponin derivative, has demonstrated potent anticancer activity by inhibiting cancer cells growth and inducing apoptosis via augmenting the Bax/Bcl-2 ratio in human cervical cancer cells." (PMID 39820585, 2025).
cervical carcinoma (continued). "PS VII induces cervical cancer cell apoptosis by modulating caspases, Bax, and Bcl-2, indicating its therapeutic potential." (PMID 41425709, 2025). "This study is also the first to investigate the changes in caspase‐9 protein activity and Bax/Bcl‐2 ratio regarding cervical cancer with the Centaurea genus." (PMID 40666823, 2025). "Previously, a spirostanol saponin derivative has been shown to inhibit cancer cell growth and induce apoptosis by increasing the Bax/Bcl-2 ratio in human cervical cancer cells." (PMID 39820585, 2025). "In cervical cancer, a lower dose of cisplatin is feasible when combined with BCL2 silencing as an adjuvant treatment to reduce resistance." (PMID 39970625, 2025). "Studies have shown that the overexpressed tumor suppressor PCBP1 favored the production of long isoforms of p73 in human cervical carcinoma cells, thereby inducing upregulated ratio of Bax/Bcl-2, the release of cytochrome c and the expression of caspase-3." (PMID 38933923, 2024). "Neoechinulin A can induce apoptosis in human cervical cancer Hela cells through down-regulation of Bcl-2 expression, up-regulation of Bax expression, and activation of the caspase-3 pathway." (PMID 38792694, 2024). "Specifically, the genes ABL1, BAX, FASN, and PLAU exhibited abnormally high expression levels in cervical cancer specimens, in stark contrast to BCL2, IGF1, and NTRK3, which were markedly under-expressed." (PMID 38988712, 2024). "In HeLa cervical cancer lines, scopoletin treatment was found to considerably upregulate Bax expression, while it downregulated the expression of Bcl-2." (PMID 39364049, 2024). "In a human cervical cancer xenograft model, FA treatment was found to reduce tumor weight in a dose-dependent manner, increase miR-34a expression, downregulate Bcl-2 protein expression, and upregulate caspase-3 protein expression." (PMID 37202657, 2023). "Crocin, a carotenoid pigment of saffron, induces cervical cancer cell apoptosis by upregulating Bax and downregulating BCL2 and miR-365a-3p." (PMID 36612314, 2023). "The over-expression of human CB2 promoted apoptosis of cervical cancer cells via up-regulating the Bax, Bad expressions and down-regulating the Bcl-2 expression." (PMID 37740231, 2023). "Other studies have found that Eug has a pro-apoptotic effect on cervical carcinoma cells by downregulating the expression of the Bcl-2 protein, increasing the expression of Bax, and activating caspase-3 and -9." (PMID 37896013, 2023). "C3G had inhibitory effects on cervical cancer, and the level of Bcl-2 protein decreased, which activated cle-caspase-3." (PMID 36677726, 2023). "Silencing GRP78 followed by treatment with cisplatin causes more than 80% of cervical cancer cells to undergo apoptosis with upregulated caspase 3 and CHOP expression as well as downregulated BcL-2 expression." (PMID 37858217, 2023). "Increased beclin‐1 expression induces BCL2 to trigger apoptosis and enhances the effect of anticancer drugs in cervical cancer." (PMID 37484971, 2023).